CRP (C-reactive protein)
Diseases named in the same sentence as CRP in open-access papers (continued):
Sharing a sentence is not in itself a finding about the gene and the disease.
viral infections (continued). "Especially, the median levels of CRP (68.89 mg/L) and SAA (280.75 mg/L) in the bacterial infection group were significantly higher than those of CRP (20.26 mg/L) and SAA (81.16 mg/L) in the viral infection group and the healthy control group (CRP = 1.67 mg/L; SAA = 2.96 mg/L; p < 0.05)." (PMID 41308272, 2025). "CRP values >20 mg/L may indicate the possibility of a bacterial LRTI, though clinical judgement should be used as CRP levels can also be elevated in viral infections (although CRP elevations due to viral infections typically remain below 20 mg/L)." (PMID 40436444, 2025). "Among them, five were due to viral infections (including two with SARS‐CoV‐2), one due to elevated CRP levels combined with fever of unknown origin, and one due to gastroenteritis." (PMID 39520275, 2025). "NiV-infected animals generally had higher C-reactive protein (CRP) and lower albumin levels (corresponding to positive and negative acute phase proteins, respectively), indicating the body’s response to active viral infection, and also high blood urea concentrations, suggesting renal dysfunction." (PMID 39870114, 2025). "While CRP may rise in response to various inflammatory stimuli, PCT levels remain low in viral infections due to suppression by interferon-gamma (IFN-γ)." (PMID 40647525, 2025). "However, these tests, especially CRP, have low specificity and low positive predictive value (PPV) for bacterial infection and can be elevated in viral infections." (PMID 41044751, 2025). "CRP has a lower specificity than procalcitonin and can be elevated in bacterial or viral infections and in cases of non-infective inflammatory conditions, including DKA." (PMID 39946377, 2025). "C-reactive protein and WBC counts were unreliable in distinguishing bacterial or viral infections." (PMID 40142520, 2025). "This suggests that when MxA or MxA/CRP levels are elevated, it is not sufficient to distinguish between isolated viral infections and mixed infections." (PMID 40046054, 2025). "Traditionally, higher levels of CRP would be taken as a sign of bacterial rather than viral infection." (PMID 38533136, 2024). "Although elevated levels of CRP in the blood can indicate inflammation in the body, it is not specific to differentiating between bacterial and viral infections." (PMID 39201697, 2024). "For instance, peak CRP ranged from 15.4 mg/L in viral infections without antibiotics to 140.9 mg/L in Gram-negative bacteremia with antibiotics." (PMID 39467995, 2024). "CRP levels can be elevated in both bacterial and viral infections, as well as other inflammatory conditions, making it a nonspecific marker of inflammation." (PMID 39201697, 2024). "In the present study, we examined the trajectory of CRP in hospitalized patients who have either had a confirmed bacteremia, a confirmed viral infection, or a non-bacteremic infection/inflammation." (PMID 39467995, 2024). "Increased CRP levels were indicative of bacterial infection while increased MxA levels were indicative of viral infection without regard to CRP levels." (PMID 39441193, 2024). "In this study, we characterized the trajectories of CRP during acute infections, under bacteremia, viral infections, or no detected bacteremia." (PMID 39467995, 2024). "Serological tests such as C-Reactive Protein (CRP) indicate any viral infection in the body and are not specific for the COVID-19 virus." (PMID 36872932, 2023). "If high CRP values (>100 mg/L) are suggestive of severe bacterial infection, lower values can be found in both viral infections and non-infectious diseases." (PMID 37685368, 2023). "This indicates that CRP levels below 200 mg/L do not discriminate bacterial pneumonia or superinfection from sole viral infection, and further studies on reliable predictors to support decisions to refrain from antibiotics are needed." (PMID 38152664, 2023).
viral infections (continued). "Moreover, LCN2 was superior to other biomarkers, such WBC, CRP, procalcitonin or CD64 expression on neutrophils in the distinction between bacterial and viral infection." (PMID 37317134, 2023). "In this study, 78 samples, namely, 28 bacterial, 12 viral, and 38 bacterial-viral infection samples with complete procalcitonin (PCT), C-reactive protein (CRP) and routine blood data, were used for analysis of inflammation indicators and types of infectious pathogens." (PMID 37822360, 2023). "CRP and PCT are the most frequently endorsed biomarkers for identifying bacterial infections in children because their levels are higher in bacterial infections than in viral infections." (PMID 37275364, 2023). "CRP, PCT, WBC, ANC, Labscore and ImmunoXpert values were significantly higher in children across both age groups with bacterial infections compared to children with viral infections or control patients." (PMID 37956117, 2023). "On the other hand, biomarkers such as erythrocyte sedimentation rate (ESR), C-reactive protein (CRP), and procalcitonin are helpful in differentiating SBI and bacteremia from viral infections in pediatric patients with fever because the results can be confirmed quickly." (PMID 36670711, 2023). "Most children with ARTI in primary care and with CRP ≥ 20 mg/L have viral infections, in which case antibiotics are not recommended." (PMID 37900677, 2023). "C-reactive protein (CRP) is a widely used biomarker for differentiating viral infections; it is a non-glycosylated protein with a molecular weight of approximately 115 kDa, composed of five identical spherical subunits non-covalently bound to each other." (PMID 37765593, 2023). "This was also the case for CRP, PCT, and NLR, and may be due to the small number of patients with viral infection in our study." (PMID 36774492, 2023). "Bacterial and viral infections are known to increase WBC, CRP, and body temperature and might therefore pose an unknown confounder on the present data." (PMID 36769654, 2023). "Increased levels of CRP or alterations of blood cell count are not specific and can be present even in the case of a viral infection." (PMID 37819417, 2023). "The currently used biomarkers that may aid in the distinction between bacterial and viral infection are mainly white blood cells (WBC) and C-reactive protein (CRP)." (PMID 37317134, 2023). "Given their affordability and accessibility, complete blood count (CBC) and c-reactive protein (CRP) tests are widely employed in both initial presentations and subsequent re-visits for cases involving seasonal viral infections, encompassing EDs and primary healthcare centers." (PMID 37818329, 2023). "GP efforts to prioritise interventions for better healthcare have so far included the recommendation to not use CRP or BC as sole routine interventions in viral infections." (PMID 35625187, 2022). "Term infants with bacterial infection were more prone to fever, cyanosis, moist rales, three concave signs, elevated C-reactive protein (CRP) levels, respiratory failure and the need for higher level of oxygen support and mechanical ventilation than those with simple viral infection (p < 0.05)." (PMID 35897053, 2022). "For CAP, C-reactive protein (CRP) and procalcitonin (PCT) have been proposed to differentiate between bacterial and viral infections but ultimately suffer from poor sensitivity and have been shown to be insufficient to diagnose CAP, let alone distinguish etiology." (PMID 35696579, 2022). "CRP, LGALS3BP, and HASPA8 have been shown to promote the innate immune response and inflammatory response and maintain cellular environmental homeostasis in viral infection." (PMID 35464963, 2022). "The combination of CRP, eosinophil, and either lymphocyte (AUC: 0.83) or HGB (AUC: 0.80 and 0.81) levels offer excellent ability to identify RNA virus infection and distinguish between bacterial and viral infections." (PMID 36095013, 2022).
viral infections (continued). "BALF IL-6, CRP, and ESR may help in diagnosing single MP, bacteria, or virus infection, respectively." (PMID 36160800, 2022). "CRP is a non-specific acute-phase protein induced by IL-6 in the liver and a marker of inflammation, bacterial or viral infection, and tissue damage." (PMID 35453906, 2022). "It usually occurs following a viral infection and is characterized by pain in the thyroid region, thyrotoxicosis symptoms, and elevated erythrocyte sedimentation rate (ESR) and, C-reactive protein (CRP) levels." (PMID 35551678, 2022). "The level of CRP was not affected in preterm infants with co-infection with bacteria and those with simple virus infection." (PMID 35897053, 2022). "Throughout the outpatient diagnosis and hospitalization, the patient did not exhibit any signs of viral infection—she was not feverous at any stage of the disease and her laboratory parameters were normal (CRP, blood count)." (PMID 35326340, 2022). "For example, the level of CRP is also increased in patients with tissue injury, virus infection, or slight local infection, but does not reach the level of BSIs." (PMID 35741271, 2022). "Currently used methods that may aid in the distinction between bacterial and viral infections are primarily white blood cell (WBC) counts, C-reactive protein (CRP) and procalcitonin (PCT) levels." (PMID 35550043, 2022). "It has been suggested that high CRP values in combination with low PCT values might be indicative of invasive fungal infections; the same might be true for viral infections." (PMID 33572924, 2021). "In the middle and late stages of FNC treatment, the WBC count, neutrophil count, monocyte count, platelet count, and CRP level in the untreated monkeys were significantly higher than those in the FNC-treated ones, suggesting a good control of viral infection by FNC in this model." (PMID 34873151, 2021). "Nevertheless, dengue and other non-viral infections can co-exist in a single sample, thus relying only on CRP should not be an exclusive criteria in differentiating both diseases." (PMID 34565334, 2021). "Either CRP ≤ 22 mg/L or PCT ≤ 0.18 ng/mL combined with rhinorrhea helps to distinguish a viral infection from a bacterial infection in hospitalized non-ICU adults with LRTIs." (PMID 34583675, 2021). "The use of antibiotic treatment in patients with proven viral disease shows that the treating physicians got no indication of infection type using the result of the first CRP test." (PMID 34863104, 2021). "In similarity to trivial viral infections, wherein the CRP levels typically remain low, SLE may manifest as oral ulcers, pleuritis/pericarditis and leukopenia, all of which commonly affect patients with viral infections." (PMID 34945133, 2021). "Furthermore, compared to PCT and CRP, IMX-BVN-1 showed both an improved stratification of bacterial infections in the Stanford ICU setting while also identifying viral infections with high accuracy." (PMID 32132525, 2020). "Other factors that influence the host defense against viral infections, such as clinical severity of the disease, CRP, D-dimer level etc., were not significantly different between the recurrent versus non-recurrent groups." (PMID 32909961, 2020). "Indeed, viral infections generally result in lower CRP-responses compared with bacterial infections, and SLE patients rarely mount a CRP-response that corresponds to their inflammatory activity or circulating IL-6 levels." (PMID 33584722, 2020). "Viral infection lead to changes in various neuroinflammation biomarkers, notably C-reactive protein and pentraxins 2, 3 were increased by htt94Q and these changes were reverted by VCE-003.2 treatment." (PMID 30899454, 2019). "Clinical laboratory tests such as white blood cell (WBC) counts and C-reactive protein (CRP) cannot unambiguously distinguish between bacterial and viral infection and may result in unnecessary treatment with antibiotics." (PMID 29531507, 2018).
viral infections (continued). "The authors concluded that, although PCT and CRP had very high accuracy for distinguishing between bacterial and viral infection, none of them were useful as an independent tool for diagnosis in patients presenting with purulent meningitis." (PMID 29891780, 2018). "PCT is known to be an accurate marker for systemic bacterial infection (independent of the pathogen) and, when compared to CRP, it is less prone to influence by viral infections, surgery, or trauma." (PMID 28264059, 2017). "Characteristics of S. pneumoniae infected subjects in relation to viral infection (negative, single and multiple) and CRP concentrationsa." (PMID 29149199, 2017). "PCT is a more specific marker of bacterial inflammation than C-reactive protein or white blood count, as its level does not rise in response to viral infection or other non-bacterial inflammation." (PMID 27333300, 2016). "C-reactive protein (CRP) and procalcitonin (PCT) are used particularly for discrimination between bacterial and viral infections and are usually found in high levels in patients with systemic bacterial infections and were also highly elevated in HFRS and CCHF patients." (PMID 27348219, 2016). "This is also consistent with findings from other primary care studies, suggesting that PCT is more specific to bacterial infections and low in patients with mainly viral infections, while CRP increases independent of infection type as a “inflammatory marker”." (PMID 27009083, 2016). "Serum CRP is not usually elevated above 10 mg/L in viral infection; however, invasive adenovirus and influenza can raise CRP to 10–80 mg/L." (PMID 26672961, 2015). "To date, C-reactive protein (CRP) has been used to make distinction between bacterial and viral infections but it has been reported as neither sensitive nor specific enough for bacterial infections." (PMID 24764729, 2014). "On the other hand, in patients with viral infections, lymphocyte showed negative correlation with CRP level (r:-0.75, p<0.05)." (PMID 24764729, 2014). "There was a significant positive correlation (r:0.76, p<0.05) between CRP and neutrophil level in the bacterial infections while there was a significant negative correlation between CRP and lymphocyte (r:-0.75, p<0.05) for viral infections." (PMID 24764729, 2014). "In viral infections, there are no reports of CRP concentrations affecting the severity of the disease." (PMID 20500875, 2010). "Studies have shown that FGF19 and CRP levels can be positively correlated in most liver diseases, but a negative correlation may occur in other conditions, such as viral infections." (PMID 39941067, 2025). "The TriVerity Bacterial and Viral scores had higher accuracy than C-reactive protein, procalcitonin or white blood cell count for the diagnosis of bacterial infection with area under the receiver operating characteristic (AUROC) of 0.83, and viral infection (AUROC = 0.91)." (PMID 41028541, 2025). "CRP is markedly elevated in bacterial infection and not so much in viral infections." (PMID 40486582, 2025). "Similarly, host inflammatory markers such as C-reactive protein (CRP) and interleukins may be used for assessing responses in bacterial or viral infection." (PMID 40141854, 2025). "There is one regulatory cleared protein-based test that measures CRP and MxA to assist in distinguishing bacterial from viral infections, but it provides a qualitative result (without any computational algorithm), lending itself to inter-operator variability and low performance." (PMID 41006994, 2025). "While CRP levels may be higher in bacterial infections compared to viral infections in some cases, it is not reliable enough to definitively distinguish between the two." (PMID 39201697, 2024).
viral infections (continued). "The goal of this study was to examine C-reactive protein (CRP) trajectories in hospitalized patients with viral infections, confirmed bacteremia (stratified by Gram-negative or Gram-positive bacteria), and non-bacteremic infections/inflammations, considering antibiotic treatment." (PMID 39467995, 2024). "Likewise, alterations in WBC counts and inflammatory markers such as C-reactive protein (CRP) and interleukin-6 (IL-6) reflect the systemic inflammatory response to viral infection and may serve as prognostic indicators of disease severity and progression." (PMID 39087175, 2024). "The laboratory values showed a significant increase in the inflammatory blood markers, including C-reactive protein 3.5 mg/dl (IQR: 5.8), fibrinogen 506 mg/dl (IQR: 167), ferritin μg/L 738 (IQR: 1078), and D-dimer 0.46 mg/L (IQR: 0.49), reflecting the presence of an acute viral infection." (PMID 37153106, 2023). "Lymphocyte–CRP ratio (LCR) is a novel inflammatory index that has the potential to assess changes in both innate and adaptive immunity, and thus may provide a more comprehensive assessment of inflammation in viral infections." (PMID 37373898, 2023). "Indeed, other old data conclude that a viral infection without bacterial involvement is very improbable if CRP > 40 mg/L, and that high CRP values rule out viral infection as a unique etiology of infection." (PMID 37873776, 2023). "However, CRP is not specific to bacterial infections and CRP levels also rise in cases of other etiologies such as surgery, rheumatic inflammation, viral diseases, systemic illnesses and cancer." (PMID 35279069, 2022). "CRP is a non-specific inflammatory marker, whereas MxA is specific for viral infections." (PMID 36010008, 2022). "Although CRP is not a specific biomarker for malaria, the response of CRP to virus infections is rather small, making it a good parameter to understand the etiology of the infection and to help differentiate malaria and dengue from similar hematology parameters." (PMID 34565334, 2021). "But with the relative progress of detection technology, further studies indicated that CRP could not distinguish a viral infection from a bacterial infection." (PMID 34583675, 2021). "A previous study conducted in Asian countries including Cambodia, Laos, and Thailand suggested elevated CRP might be used to discriminate malaria from viral infections although it could not discriminate malaria from bacterial infections." (PMID 34764364, 2021). "Therefore, for severely infected patients with elevated CRP, if using antibacterial drugs is not effective, the viral infection should be taken into account." (PMID 32972385, 2020). "However, CRP is not specific for bacterial infections and can also be elevated in viral infections and after surgery or trauma." (PMID 28264059, 2017). "CRP level is not a good prognostic factor in viral infections." (PMID 25685783, 2015). "Furthermore, compared with patients suffering from viral infections, patients with bacterial infections displayed higher concentrations of CRP and sTLR4, but not sTLR2 (groups C and D)." (PMID 25406630, 2014). "It has been widely accepted that CRP was not elevated during viral infections." (PMID 24764729, 2014). "The sensitivity, specificity, positive predictive (PPV) and negative predictive values (NPV) of CRP>5 mg/ml for bacterial mono-infection versus viral infections were 87.8% (CI95%: 78.2–94.3%), 30.8% (CI95%: 22.3–40.5%), 46.8% (CI95%: 38.3–55.4%) and 78.6% (CI95%: 63.2–89.7%), respectively." (PMID 24755844, 2014). "However, CRP reflects global innate immunity activation rather than informing specifically about the interactions between viral infections and adaptive immunity, and thus may not provide a comprehensive assessment of COVID-19 infections." (PMID 37373898, 2023).